GPR84 (G protein-coupled receptor 84)
Diseases named in the same sentence as GPR84 in open-access papers (continued):
Sharing a sentence is not in itself a finding about the gene and the disease.
steatosis (3 papers, 2020 to 2023). Increased lipid within the cytoplasm of cells. "Therefore, the mechanism underlying the progression from steatosis to ballooning maybe driven in part by GPR84 activation." (PMID 32728158, 2020). "Furthermore, the impact of PBI-4547 on steatosis was highly dependent on GPR84 since this protective effect was lost in KO mice." (PMID 32728158, 2020). "Interestingly, GPR84 was also shown to be crucial for the transition from steatosis to ballooning in NAFLD." (PMID 32728158, 2020). "Interestingly, therapeutic GPR84 inhibition in both NASH models demonstrated major effects on inflammation and fibrosis, while the effects on steatosis appeared minor." (PMID 32316235, 2020). "In diseased livers, GPR84 gene expression was associated with the inflammation grading of the NAFLD Activity Score (NAS), as well as with the fibrosis stage, but not with steatosis." (PMID 32316235, 2020). "GPR84 antagonists weakly suppress NASH, and HFD feeding in Gpr84–/– mice weakly restores fibrosis, but not steatosis and inflammation." (PMID 36480287, 2023). "Our results also show that steatosis establishment was independent of GPR84 suggesting that other receptors than GPR84 that are targeted by PBI-4547, such as GPR40 or PPARs, may be involved in adiponectin secretion and the process of steatosis." (PMID 32728158, 2020).
type 2 diabetes (3 papers, 2020 to 2024). "The present study demonstrated that GPR84 deficiency exacerbates HFD‐induced type 2 diabetes in mice and that the metabolic improvement effects due to MCT intake are partially mediated by GPR84 activation." (PMID 39512839, 2024).
viral infection (3 papers, 2015 to 2025). "Furthermore, GPR84 has been implicated in the immune responses to both bacterial and viral infections." (PMID 39858878, 2025). "Thus, loss of GPR84 in bats might be part of the mechanism protecting against excessive inflammation in response to the increased epithelial permeability caused by a viral infection and accompanied by invasion of bacterial pathogens." (PMID 36164652, 2022). "In the context of viral infection, GPR84 expression was upregulated in neutrophils from COVID-19 patients, as revealed by the RNA sequencing of bronchoalveolar lavage fluid." (PMID 39858878, 2025). "Many studies show that GPR84 expression is increased under pro-inflammatory conditions, including bacterial and viral infections." (PMID 36164652, 2022). "Other genes, including Gpr84 and Birc3, as well as expressed transcripts AW112010 and BC023105 were consistently upregulated in activated microglia and astrocytes and were also upregulated in the CNS following virus infection." (PMID 26214311, 2015). "In addition, other genes including Birc3 and Gpr84 as well as two expressed sequences AW112010 and BC023105 were found to be induced in both microglia and astrocytes and were upregulated in the CNS following virus infection." (PMID 26214311, 2015).
atherosclerosis (2 papers, 2018 to 2021). A disease characterized by the build-up of fatty material and calcium deposition in the arterial wall resulting in partial or complete occlusion of the arterial lumen. "GPR84 agonists also increase cholesterol efflux and are reported to be protective in atherosclerosis." (PMID 34943862, 2021). "Atherosclerosis is a chronic inflammatory disease and to evaluate the expression of GPR84 in this condition, ApoE−/− mice were fed a HFD for 6 and 12 weeks, then sacrificed and tissues collected." (PMID 29973940, 2018). "Our demonstration that synthetic agonists of GPR84 activate pro-inflammatory signaling and cytokine release in already activated macrophage populations suggests that detailed examination of GPR84 expression and signaling is merited in murine and human atherosclerosis." (PMID 29973940, 2018).
chronic kidney disease (2 papers, 2020 to 2021). Impairment of the renal function secondary to chronic kidney damage persisting for three or more months. "In an adenine‐induced chronic kidney disease mouse model, deletion of Gpr84 reduced kidney fibrosis compared with wild type, indicating a deleterious role for GPR84 in renal nephropathy." (PMID 33960725, 2021). "In the relationship between inflammation and fatty acid sensing or regulation, the ligands for GPR84 play significant roles and may represent a novel drug target for treating immune-mediated diseases and fibrosis, including the experimental neuro-inflammatory model or chronic kidney disease." (PMID 33344384, 2020).
colon carcinoma (2 papers, 2022 to 2024). "We next sought to determine the in vivo role of GPR84 in anti-tumor immunity using the MC38 colon carcinoma model." (PMID 38349405, 2024). "Matching these clinical observations, our flow cytometry studies using the MC38 colon cancer model showed that the protein level of GPR84 is abundant in tumor samples, but significantly lower in spleen, bone marrow, and blood (Supplemental 1E)." (PMID 38349405, 2024). "To examine the role of GPR84 in TAMs, we next compared differentially expressed genes (DEGs) between GPR84high and GPR84low tumor-infiltrating macrophages from the same colon cancer scRNA-seq datasets." (PMID 38349405, 2024). "To confirm this finding in a larger cohort, we used the web server, GEPIA2 to interrogate The Cancer Genome Atlas (TCGA) human cancer and the Genotype Tissue-Expression (GTEx) database for GPR84 expression, which exhibits significantly higher expression in colon tumors than normal tissues." (PMID 38349405, 2024).
colorectal cancer (2 papers, 2023 to 2025). A primary or metastatic malignant neoplasm that affects the colon or rectum. "The expression of GPR84 in bone marrow-derived monocytes/macrophages (BMMs) can inhibit osteoclast formation; however, its role in bone metastasis of colorectal cancer (CRC) is still unknown." (PMID 36593458, 2023).
dyslipidemia (2 papers, 2023). "To confirm that changes in insulin sensitivity are associated with dyslipidemia in BAT, we analyzed genes related to FA metabolism in the BAT of WT and GPR84-KO mice." (PMID 37856216, 2023). "The exact contribution of endogenous MCFAs and the receptor GPR84 in controlling metabolic syndrome was previously unclear." (PMID 36480287, 2023).
endotoxemia (2 papers, 2018 to 2020). "We report that in a murine model of low-dose endotoxemia, all tissues assessed displayed a significantly increased expression of Gpr84 at 2 and 8 h post LPS injection." (PMID 29973940, 2018). "To assess the pattern of Gpr84 expression in mice during acute inflammation, we carried out an experimental model of endotoxemia." (PMID 29973940, 2018).
lung carcinoma (2 papers, 2022 to 2023). "And it showed that GPR84 deletion markedly reduced tumor growth in lung cancer and melanoma tumor models." (PMID 37105980, 2023). "We first analyzed the expression level of GPR84 across cancers and found that the expression level of GPR84 was higher in glioma, breast cancer, liver cancer, lung cancer, pancreatic cancer and stomach cancer than in normal tissues." (PMID 36061172, 2022). "We found that expression level of GPR84 was higher in some tumor tissues than in normal tissues, such as glioma, breast cancer, liver cancer, kidney cancer, lung cancer, pancreatic cancer and stomach cancer." (PMID 36061172, 2022).
non-alcoholic steatohepatitis (2 papers, 2020 to 2025). "We aimed at deciphering the role of GPR84 in the pathogenesis of non-alcoholic steatohepatitis (NASH), exploring its potential as a therapeutic target." (PMID 32316235, 2020). "However, in chronic diseases such as osteoarthritis, non-alcoholic steatohepatitis, and Brucella abortus infection, GPR84 plays a role in modulating inflammation by reducing the expression of pro-inflammatory factors (such as TNF-α), thereby alleviating disease progression or promoting infection." (PMID 39858878, 2025).
non-small cell lung carcinoma (2 papers, 2023). A group of at least three distinct histological types of lung cancer, including non-small cell squamous cell carcinoma, adenocarcinoma, and large cell carcinoma. "Notably, the GPR84+ cell frequencies in peripheral blood from patients with esophageal squamous cell cancer (ESCC) and non-small cell lung cancer (NSCLC) were significantly higher than those in samples from healthy controls." (PMID 37105980, 2023).
autoimmune hepatitis (1 paper, 2025). Hepatitis caused by autoantibodies. "Given the clinical relevance of our findings, future studies should focus on further validating the efficacy and safety of GPR84 inhibitors in preclinical models and exploring their potential for clinical trials in autoimmune hepatitis." (PMID 40369402, 2025).
bladder cancer (1 paper, 2024). "We further demonstrated that pharmacological activation of GPR84 reshapes TAMs to improve PD-1 blockade therapy in both colon and bladder cancer models." (PMID 38349405, 2024). "In addition, our observation excludes the possibility of GPR84-mediated direct cytotoxicity against cancer because treatment with 6-OAU cannot induce apoptosis in both MC38 colon and MB49 bladder cancer cell lines." (PMID 38349405, 2024).
fibrosis (1 paper, 2020). the formation of excess fibrous connective tissue in an organ or tissue in a reparative or reactive process. "Moreover, GPR84-deficient mice were protected from organ fibrosis in experimental kidney injury." (PMID 32316235, 2020).
food allergy (1 paper, 2021). Gastrointestinal disturbances, skin eruptions, or shock due to allergic reactions to allergens in food. "Short-chain fatty acid (SCFA) receptors (GPR41, GPR43, and GPR109A) and GPR84 were implicated in food allergy." (PMID 34721374, 2021).
Glucose intolerance (1 paper, 2024). Glucose intolerance (GI) can be defined as dysglycemia that comprises both prediabetes and diabetes. "In support our current results, we previously reported that GPR84 was expressed in the ileum and oral administration of C10:0 improved glucose intolerance by GLP‐1 secretion through intestinal GPR84 activation." (PMID 39512839, 2024).
gram-negative bacterial infections (1 paper, 2020). Infections caused by bacteria that show up as pink (negative) when treated by the gram-staining method. "As markers GPR84, KLRK1, and TDRD9 were not represented in dataset E-GEOD-6269 (Affymetrix chip HG-U133A), interaction profiling of these genes was omitted from the gram-positive and gram-negative bacterial infection group dataset." (PMID 32318053, 2020).
Hepatitis (1 paper, 2025). Inflammation of the liver. "This approach allowed us to investigate whether BM-derived cells lacking GPR84 are critical in mitigating Con A-induced hepatitis." (PMID 40369402, 2025).
hepatocellular carcinoma (1 paper, 2020). A malignant tumor that arises from hepatocytes. "GPR84, a protein-coding gene of the metabolic G protein-coupled receptor family, can be regarded as a potential signature for the prognostic prediction of hepatocellular carcinoma." (PMID 33169786, 2020).
Hypoinsulinemia (1 paper, 2024). A decreased concentration of insulin in the blood. "Therefore, although GPR84 deficiency suppressed HFD‐induced weight gain, it aggravated the HFD‐induced increases in plasma glucose and lipid levels, thereby impairing glucose homeostasis and hypoinsulinemia under HFD feeding." (PMID 39512839, 2024).
Kawasaki disease (1 paper, 2020). A rare inflammatory disease characterized by an acute febrile, systemic, self-limiting, medium-vessel vasculitis primarily affecting children. "However, to the best of our knowledge, the up-regulation of GPR84 on leukocytes with regard to Kawasaki disease was first noted in this study." (PMID 33344384, 2020).
Lewis lung carcinoma (1 paper, 2023). "Detections of spleen samples derived from Lewis lung carcinoma (LLC) and B16F0 models also had given the same evidence that GPR84 is highly expressed in MDSC than other immune cells." (PMID 37105980, 2023).
lymph-node metastasis (1 paper, 2023). "Patients with lymph-node metastasis showed higher GPR84 expression in tumor tissues than non-metastatic patients." (PMID 37105980, 2023).
lymphoma (1 paper, 2024). A malignant (clonal) proliferation of B- lymphocytes or T- lymphocytes which involves the lymph nodes, bone marrow and/or extranodal sites. "In addition, one recent in vitro CRISPR screen has identified GPR84 as an enhancer for phagocytosis of Ramos lymphoma cells; which can be escaped by overexpression of adipocyte plasma membrane-associated protein (APMAP)." (PMID 38349405, 2024).
malignant melanoma (1 paper, 2023). "It was also found that treatment with GPR84 antagonist strangely inhibited melanoma growth and decreased lung metastasis of malignant melanoma." (PMID 37105980, 2023).
Mm (1 paper, 2025). "Furthermore, from our studies in an in vitro macrophage Mm infection model, it appears that GPR84 inhibits pro-inflammatory cytokines expression and increases intracellular lipid droplet (LD) accumulation, thereby promoting intracellular bacterial survival." (PMID 39858878, 2025).
mycobacterial infection (1 paper, 2025). "And GPR84 deficiency is beneficial to increase the expression of pro-inflammatory cytokines during mycobacterium infection." (PMID 39858878, 2025). "Our study found that GPR84 deficiency restricts the progression of mycobacterial infection, but the delineation of the downstream signaling pathways activated by GPR84 during mycobacterial infections will require subsequent investigation." (PMID 39858878, 2025). "In conclusion, our study demonstrates that GPR84 exacerbates the progression of mycobacterial infection." (PMID 39858878, 2025). "The results indicated a significant upregulation of GPR84 mRNA in the blood of these patients, suggesting the potential involvement of GPR84 in the progression of mycobacterial infection." (PMID 39858878, 2025). "Therefore, we conducted an initial exploration of the role and mechanism of GPR84 in mycobacterium infection, providing new insights into the host–pathogen interaction in mycobacterium infection." (PMID 39858878, 2025). "Further exploration of the regulatory mechanisms by which GPR84 influences the host response to mycobacterial infection may offer novel avenues for the development of host-directed anti-tuberculosis therapeutics." (PMID 39858878, 2025). "We report that GPR84 expression is markedly upregulated during mycobacterial infections." (PMID 39858878, 2025). "In this study, we found that GPR84 plays a harmful role for hosts in mycobacterial infections." (PMID 39858878, 2025). "Additionally, the genes Mgll, Dgat2, Slc27a6, and Stard10 have been implicated in lipid metabolism, indicating that lipid metabolism may be disrupted in Gpr84−/− BMDMs during mycobacterial infection." (PMID 39858878, 2025). "However, no studies have yet reported on the function of GPR84 in mycobacterium infection." (PMID 39858878, 2025).
neuropathic pain (1 paper, 2020). Chronic pain caused by damage to nerve fibers. "In the present study, we determined the role of DOK3 in activating microglia-induced neuropathic pain and investigated the underlying mechanisms associated with GPR84." (PMID 33281117, 2020).
osteosarcoma (1 paper, 2024). A usually aggressive malignant bone-forming mesenchymal neoplasm, predominantly affecting adolescents and young adults. "Compared to the sham group, the SNL group had higher gene expression levels of Gadd45g (growth arrest and DNA-damage-inducible 45 gamma) and Fos (FBJ osteosarcoma oncogene), while it had lower gene expression levels of Igf1, Ccl2, Hdac2, Rtn4rl1, Nfkb2, Gpr84, Pik3cg, and Abcc8." (PMID 38790607, 2024).
reflux esophagitis (1 paper, 2022). "GPR84 is suspected to be involved in several inflammatory and metabolic disorders, including acute lung injury, neuropathic pain, atherosclerosis, reflux esophagitis, as well as kidney and pulmonary fibrosis." (PMID 34912006, 2022).
renal fibrosis (1 paper, 2022). A final common manifestation of a wide variety of chronic kidney diseases characterized by glomerulosclerosis and tubulointerstitial fibrosis. "In Ffa1r−/− or Gpr84−/− knockout mice used as models of kidney fibrosis, FFA1R revealed to have a protective effect against renal fibrosis, whereas GPR84 had the opposite effect." (PMID 35163697, 2022).
scrapie (1 paper, 2016). A fatal disease of the nervous system in sheep and goats, characterized by pruritus, debility, and locomotor incoordination. "Initially we quantified the amount of detectable gliosis in the thalamus of preclinical scrapie-infected mice, using Gfap and Vimentin as markers of astroglia, and Gpr84 and Cx3cr1, as markers of microglia." (PMID 27046083, 2016). "Furthermore, although activated microglia were seen in BE infected mice by IHC, based on the expression levels of microglial markers, Gpr84 and Aif1, the number of activated microglia was less in BE than in scrapie." (PMID 27046083, 2016).
tuberculosis (1 paper, 2025). A chronic, recurrent infection caused by the bacterium Mycobacterium tuberculosis. "We found that GPR84 is induced in whole blood samples from tuberculosis patients and Mycobacterium marinum (Mm)-infected macrophage models." (PMID 39858878, 2025). "Subsequently, we assessed the expression of GPR84 mRNA in whole blood samples obtained from patients diagnosed with tuberculosis." (PMID 39858878, 2025).
vasculitis (1 paper, 2020). "Inflammatory molecules of haptoglobin (HP), C-Type Lectin Domain Family 4 Member D (CLEC4D), and G-protein coupled receptor 84 (GPR84) are glycoproteins involved in cardiovascular disease and vasculitis." (PMID 33344384, 2020).